IL4 (interleukin 4)
Diseases named in the same sentence as IL4 in open-access papers (continued):
Sharing a sentence is not in itself a finding about the gene and the disease.
Immunodeficiency (11 papers, 2013 to 2025). Failure of the immune system to protect the body adequately from infection, due to the absence or insufficiency of some component process or substance. "Additionally, we found that STAT3 mutations regulate the phenotype and function of immune cells by modulating CX3CR1 and IL-4, further elucidating the mechanisms of immune deficiency and high IgE levels in patients with STAT3 mutations." (PMID 41212476, 2025). "Since γc is shared by receptors for IL-4, IL-7, IL-9, IL-15, and IL-21 and a loss of γc function causes immunodeficiencies in both humans and mice, it is anticipated that knockdown of γc may lead to severe systemic side effects." (PMID 24223832, 2013). "By contrast, immunosuppressive cytokines such as IL-4, IL-10 and TGF-β produced by M2 macrophages are associated with immunodeficiency and the persistence and advanced infection with pathogens including MTB." (PMID 35420971, 2022). "Studies have shown that YPFS can inhibit the secretion of IFN-γ and IL-4, and affect the total number of T cells, which is reflected by the decrease of Th1 and Th2 cytokine level to mediate immunodeficiency disease." (PMID 31885639, 2019). "al. have studiedimmunological factors including IL-4, IL-5, IL-13 and PGE2 in vaginal discharge in women withRVVC proposing that infected cases had a specificlocal immune deficiency in that area." (PMID 28868834, 2017). "Some authors have speculated that in patients with an immunodeficiency due to hematologic disease, a trigger, such as a drug or a virus, induces cytokine production with an excess of interleukin (IL)-4 and IL-5, resulting in an altered immune response with eosinophil predominance." (PMID 41375673, 2025). "The molecular cause for the selectively impaired production of IL-21, IL-4, and IL-10 is not understood yet, but the high expression of PD-1, a negative regulator of T cell activation might interfere with cytokine secretion and contribute to the immunodeficiency." (PMID 29375547, 2017).
lung adenocarcinoma (11 papers, 2012 to 2025). A carcinoma that arises from the lung and is characterized by the presence of malignant glandular epithelial cells. "In addition, lung adenocarcinoma patients increased both plasma concentrations of IL-2, IL-4, IL-6, and IL-10, and proportions of Latency Associated Peptide (LAP) TGF-β subset of CD4+CD25+CD127− Treg cells, which overexpressed LAP TGF-β." (PMID 26582240, 2015). "Melittin‐MIL‐2 injection upregulated IFN‐γ levels as well as inhibited IL‐4 secretion, facilitating the development of Th1 subtypes relative to Th2 cells in lung adenocarcinoma microenvironment." (PMID 39003635, 2024). "In lung adenocarcinoma patients, compared with smoking subjects, the concentrations of IL-2, IL-4, IL-6, and IL-10 were increased." (PMID 26582240, 2015). "The importance of Th2 cytokines, including IL-4, IL-10, and IL-13, in the regulation of the protumor functions of TAMs has also been demonstrated in human lung adenocarcinomas." (PMID 26242181, 2015). "Our results showed higher levels of proinflammatory (IL-2 and IL-6) and anti-inflammatory (IL-4 and IL-10) cytokines in lung adenocarcinoma patients compared with smoking subjects." (PMID 26582240, 2015). "Basophils co-cultured with human lung adenocarcinoma A549 released IL-4 and IL-13." (PMID 40873585, 2025). "Furthermore, the regulation of the necroptosis pathway, which is closely associated with the inflammatory environment induced by IL-4/IL-13, may be involved in PLK1-mediated modulation of the immune microenvironment in lung adenocarcinoma (LA) patients." (PMID 37744268, 2023). "In our previous study, we reported increased levels of IL-4, IL-6, IL-10, and TGF-β detected in the peripheral blood of lung adenocarcinoma patients." (PMID 33167343, 2020). "We assess the effect of lung adenocarcinoma cells on TAM through detecting the expression of SHP2, p- STAT1, p-STAT3, p-STAT5, p-STAT6, IL-4, IL-10, Cathepsin-L, Cathepsin-S, Cathepsin-K and Arginase-1 in each group of THP1 cells cocultured with and without A549 cells by western blot." (PMID 38747738, 2024).
lymphopenia (11 papers, 2014 to 2023). Reduction in the number of lymphocytes. "In the first IL-4 transgenic mice, overexpression of IL-4 lead to lymphopenia and death, so that transgenic IL-4 expression had to be attenuated in order to establish transgenic mouse strains." (PMID 31237933, 2019). "Having found lymphopenia and higher-than wt IL-4 serum levels and production by T cells in certain γδ T cell-deficient mouse strains (and current study), we examined αβ T cells in the spleen focusing on MP cells (gating strategy in S8 Fig)." (PMID 31237933, 2019). "AIMP CD8+ αβ T cells that arise as a result of lymphopenia-induced peripheral homeostatic proliferation, “virtual memory” (VM) MP T cells in the periphery, and IL-4-dependent innate MP αβ T cells in thymus and periphery, all differ in their gene expression." (PMID 31237933, 2019). "Unlike conventional memory T cells which are generated upon encounter with their cognate peptide antigens on classical MHC molecules, ‘innate’ memory T cells arise under homeostatic conditions in response to neonatal lymphopenia, high levels of IL-4 or exposure to self-antigens in naïve mice." (PMID 38127067, 2023). "This reduction and its downstream cellular and molecular consequences—possibly in addition with the general lymphopenia of CCT8T−/− mice—explains mechanistically the animals’ inability to expel H. polygyrus via a robust immune response that generates sufficient IL-4." (PMID 34083746, 2021). "Consistently, we show here that removing IL-4 abrogated their splenic lymphopenia." (PMID 31237933, 2019). "Additionally, we found that IL-2 and IL-4 were elevated and exceeded the normal upper limit at the same time point of recovery of lymphopenia before discharge, indicating that they might be beneficial to the recovery process." (PMID 33461503, 2021). "Steroid‐induced lymphopenia occurs via inhibition of T‐cell activation by inhibition of IL‐2, IL3, IL‐4, and IL‐6,43 and suppression of dendritic cell maturation and function." (PMID 35478442, 2022).
nephritis (11 papers, 2013 to 2024). Inflammation of renal tissue. "IL-4 levels correlated with hypercellularity in nephritis patients suggesting Th2 cells play an active role in disease progression." (PMID 35444658, 2022). "Basophils control a constitutive TH2 skewing in Lyn−/− mice in an IgE- and IL-4-dependent manner, which contributes to the development of lupus-like nephritis." (PMID 35444641, 2022). "In the animal LN model, anti-inflammatory cytokines, such as TGF-β and IL-4, were overproduced to repair kidney inflammation, leading to fibrosis." (PMID 35095868, 2021). "Correlation analyses displayed that TGF-β1, TGF-β2, IL-10, IL-4/13A, and IL-4/13B gene expression were positively correlated with the p-TOR Ser2448, suggesting that AFB1 aggravated spleen and head kidney inflammation partly be associated with the inhibition of TOR signaling in fish." (PMID 36330527, 2022). "Similarly, administration of IL-4 neutralizing antibodies or deletion of STAT6 in NZM2410 mice resulted in the abrogation of nephritis symptoms." (PMID 35444658, 2022). "Renal cortical IFN-γ, IL-4, IL-10, IL-17, and Foxp3 gene expressions were significantly higher in the WKY-HBSS rats than in WKY rats without nephritis, as assessed by real-time RT-PCR." (PMID 23826305, 2013).
parasite (11 papers, 2008 to 2022). "Under steady state conditions, the amount of IL‐4 in the circulation is very low, compared to conditions such as parasite infections." (PMID 36063138, 2022). "IL-4 plays a crucial role in promoting the secretions of IFN-γ at the late stage of parasite infections." (PMID 35265084, 2022). "In our study, mice were sacrificed 8 weeks after infection (61 days post parasite infection), the peak release of Th2-type cytokines such as IL-4 and IL-10, was measured in this work." (PMID 27378927, 2016). "Several reports have suggested the pivotal role of IL-4 in host protective responses against parasite infections." (PMID 25811778, 2015). "Indeed, in type-2-skewed responses, such as some parasite infections in the gut, IL-25 clearly drives the inflammation upstream of IL-4, IL-5, and IL-13 and therefore acts as a pro-inflammatory cytokine." (PMID 22539101, 2012).
Salmonella Infections (11 papers, 2008 to 2023). Infections with bacteria of the genus SALMONELLA. "Here we report a novel role of IL-4 for the control of intracellular Salmonella infection in macrophages by modulating L-arginine-dependent metabolic pathways." (PMID 37190073, 2023). "Meanwhile, other cytokines like IL-4 and IL-10 inhibit the host defenses against salmonella infections." (PMID 33396722, 2020). "Meanwhile, our results revealed reductions in the expression of other cytokine genes; IL-4 and IL-10, which inhibit host defenses against salmonella infections." (PMID 33396722, 2020). "After Salmonella infection, the amount of IL-4 and IL-21 was strongly upregulated in CD4+ T cells of MyD88−/−, but not MyD88+/+, mice." (PMID 29973931, 2018). "This constitutive production of TNF-α and IL-4 reduced significantly 6h after Salmonella infection, whereas it was maintained 6h after Hc-ES stimulation, and then decreased 12h later (data not shown)." (PMID 24223964, 2013). "IL-4 pathway, which is used for in vitro differentiation into DCs was also up-regulated during Salmonella infection." (PMID 23284947, 2012). "Overall, these data illustrate that the IL-4 and IL-9 signaling pathway associated with TH2 immune response was activated by pathogenic Salmonella infection in colon mucosa." (PMID 21172007, 2010). "However, herein we uncover a novel role of IL-4 in the control of intracellular Salmonella infection in macrophages by modulation of L-arginine-dependent metabolic pathways." (PMID 37190073, 2023). "Hence, IL-4 and IL-9 signaling pathway activated in mouse mucosa with Salmonella infection provides more comprehensive information about how the Th2 immune system interplays with signaling transducers in colon mucosal inflammation." (PMID 21172007, 2010). "In summary, we found a prominent induction of ARG1 in macrophages upon Salmonella infection and an opposite regulation of ARG1 by IL-4 and IFNγ." (PMID 34359992, 2021). "Similar effects were elucidated in wild-type as well as in IL-12 KO and IL-4 KO BALB/c mice, where IL-12 was indispensable for the induction of a protective Th1 response against Salmonella infection." (PMID 18990205, 2008). "In the three recipients surviving Salmonella infection, their serum IFNγ increased from 14.2, 90.2, and 108 pg/mL before challenge to 1356, 568, and 190 pg/mL after challenge, respectively, whereas serum IL4 was not detectable before or after challenge." (PMID 33804435, 2021). "The CD1b- L-DCs constitutively expressed GATA-3, TNF-α, IL-23 and IL-4 genes which were down-regulated after Salmonella infection, but not after stimulation with helminth secretions." (PMID 24223964, 2013). "In contrast to our Salmonella infection model, induction of Arg1 in L. major infection in BALB/c mice was driven by a strong Th2 response releasing IL-4 and IL-13 and not by the pathogen itself." (PMID 34359992, 2021). "Salmonella infection reduced the constitutive expression of TNF-α and IL-4 mRNA in CD1b- L-DCs, whereas this expression was not affected by helminth secretions." (PMID 24223964, 2013).
silicosis (11 papers, 2006 to 2025). Silicosis is a respiratory disease caused by breathing in (inhaling) silica dust. "In humans, no clinical trials testing the possible role of IL4 or IL13 in silicosis are known, but some IL4 gene polymorphism studies indicate some susceptibility in CWP." (PMID 36675056, 2023). "Our data support that some cytokines (IL-4, IL-13 and IL-9) associated with a TH2 response are increased in the plasma of patients with silicosis, while cytokines associated with the TH1 response are practically not altered." (PMID 36675056, 2023). "Contrasting opinions on the exact roles of Th2 cytokines IL-10 and IL-4 in the course of silicosis development have thus far been proposed." (PMID 36311760, 2022). "Patients with asbestosis have elevated expression of IL-10 in their AMs, whereas patients with silicosis showed increased levels of IL-10, IL-4, IL-5, and IL13 in their serum." (PMID 32625201, 2020). "The level of IL-4 increased gradually during the process of silicosis and reached peak at day 56 in silica-treated group." (PMID 21072213, 2010). "Patients with silicosis also had increased levels of IL-4, IL-5 IL-10, and IL-13 in their serum." (PMID 35547729, 2022). "Similarly with IL-4, abundance of IL-4 signaling following quartz instillation as well as decreased IL-4 mRNA expression in lymph nodes of rats with silicosis have been reported." (PMID 36311760, 2022). "Previous studies have shown that the incidence of silicosis may be influenced by genetic factors such as IL-4, IL-1, and tumor necrosis factor (TNF)-α." (PMID 26496436, 2015). "Besides, in silica-treated mice, the level of IL-4 increased gradually during the process of silicosis and reached peak at day 56, which suggested that Th2 immune response played some role during the fibrotic process of silicosis." (PMID 21072213, 2010). "Garn and colleagues noted decreased IL-4 mRNA in the lymph nodes of rats with silicosis." (PMID 16396683, 2006). "Silicosis patients’ exosomal miR125a-5p, TGF-β1, IL-17 A, and IL-4 blood levels were elevated and related to silicosis progression." (PMID 40504442, 2025). "The levels of IL-4 and Th2 transcription factor GATA3 were suppressed especially in the late fibrosis stage, when the mice with developing silicosis already shifted the Th balance to favor Th2 predominance." (PMID 27354007, 2016). "IL-4-/- and IL-4Rα-/- mice did not, however, appear protected against the development of silicosis, suggesting that Th2 immune response is not essential for the development of this fibrotic disease." (PMID 21072213, 2010). "Changes in IL-4 have been observed by some, but not all, investigators studying silicosis." (PMID 16396683, 2006). "The primarily signals that might induce IL-4 or IL-13 in silicosis have not been identified." (PMID 16396683, 2006). "Treg cytokines (TGF-β and IL-10) and Th2 cytokines (IL-4, IL-5, and IL-13), but not Th1 cytokines (IFN-γ, IL2, and IL-12) and pro-inflammatory cytokines (IL-1β, IL-6, and TNF-α), were found to be increased in the sera of patients with silicosis." (PMID 32625201, 2020).
urticaria (11 papers, 2010 to 2025). A vascular reaction of the skin characterized by erythema and wheal formation due to localized increase of vascular permeability. "The association of LP with IL-4 (OR = 1.099, 95% CI = 1.020-1.184, p = 1.26e-02) and urticaria with IL-2 (OR = 0.712, 95% CI = 0.531-0.955, p = 2.33e-02) remained significant at the Bonferroni-corrected significance threshold (p = 0.05/2 = 0.025)." (PMID 37954607, 2023). "Studies regarding IL-31 and urticaria were mainly concerning disease severity and therapy exploitations, as basophils have been found to produce pro-inflammatory cytokines (IL-4 and IL-13), after the interaction of IL-31/IL-31R." (PMID 35742951, 2022). "Our study concerns four ILs, IL-4, IL-6, IL-8 and IL-10, simultaneously and their quantitative changes during the acute phase of urticaria as well as 2 weeks after drug administration." (PMID 24578755, 2014). "Since now there is no study in the literature describing the levels of all four ILs (IL-4, IL-6, IL-8 and IL-10) in the patients with urticaria." (PMID 24578755, 2014). "In patients showing urticaria, there is a positive correlation of IL-4 with IL-5, while that of IL-5 with IL-10." (PMID 20616938, 2010). "Therefore, its inhibition may paradoxically lead to IL-4 upregulation, potentially triggering Th2-related disorders such as AD, BP, and urticaria." (PMID 40364058, 2025). "On the other hand, when immune skin diseases served as the exposure variable, LP affected eotaxin, IL-12p70, IL-4, IL-16, and MCP-1 and urticaria affected IL-2 and MCP-1." (PMID 37954607, 2023). "To elucidate the effects of PF on the inflammatory cytokine release in urticaria, we measured the mRNA levels of IL-12, IL-6, IFN-γ, and IL-4 in skin lesions using qRT-PCR." (PMID 35222003, 2021). "There have been studies evaluating the levels of isolated ILs in patients with urticaria, but none of them compared the levels of the four ILs in the same patient (IL-4, IL-6, IL-8 and IL-10)." (PMID 24578755, 2014).
autoimmune thyroid disease (10 papers, 2011 to 2025). Inflammatory disease of the thyroid gland due to autoimmune responses leading to lymphocytic infiltration of the gland. "On the other hand, overexpression of IL-4 in thyrocytes impairs iodide uptake and increased the susceptibility to develop severe, accelerated, and spontaneous autoimmune thyroiditis in response to excessive iodide supply in an animal model of HT." (PMID 40573063, 2025). "IL-4 and IL-6 have also been implicated in autoimmune thyroid." (PMID 37513704, 2023). "Subfertile women with autoimmune thyroid disease usually express increased levels of IFNγ from pro-inflammatory Th1 immune cells, along with lower IL-4 and IL-10 from Th2 immune cells compared with control patients without antithyroid antibodies." (PMID 35351031, 2022). "A positive correlation between INF-γ and IL-4 appears to be important in the context of auto-prevention of autoimmune thyroid diseases, e.g., in the course of HT, Th1 cell activity stimulated by INF-γ increases, which can be repressed by IL-4." (PMID 40573063, 2025). "Compared to women who test negative for thyroid antibodies, women with autoimmune thyroid disease and reduced fertility typically exhibit elevated levels of pro-inflammatory immune cytokines from Th-1 cells (such as IFN-γ), along with decreased levels of IL-4 and IL-10 produced by Th-2 immune cells." (PMID 38298186, 2023).
ischemic heart disease (10 papers, 2011 to 2024). "In addition, the risk of developing ischemic heart disease (IHD) generally is associated with relatively low blood levels of Flt3 ligand, whereas, for patients suffering from abdominal obesity (AO), the relative risk of early ischemic heart disease (IHD) is linked to low levels of IL-4." (PMID 34372196, 2021). "Interleukin family was also predicted to be related to coronary artery disease, including IL 6, IL4, IL10, IL1A, and IL1B." (PMID 29861771, 2018).